WWP2 (WW domain containing E3 ubiquitin protein ligase 2)
Diseases named in the same sentence as WWP2 in open-access papers (continued):
Sharing a sentence is not in itself a finding about the gene and the disease.
glioma (5 papers, 2021 to 2025). A benign or malignant brain and spinal cord tumor that arises from glial cells (astrocytes, oligodendrocytes, ependymal cells). "CMTM5 knockdown led to increased cell viability, proliferation, migration, and invasion of glioma cells, while WWP2 silencing compromised these alterations caused by CMTM5 knockdown." (PMID 39166861, 2024). "WWP2 has been implicated in several cancers, including glioma." (PMID 39166861, 2024). "Collectively, these findings indicate that CMTM5 inhibited WWP2‐mediated LATS2 ubiquitination in glioma cells." (PMID 39166861, 2024). "Future studies should aim to overcome the limitations of this study to explore the role of CMTM5/WWP2/LATS2 signaling in glioma." (PMID 39166861, 2024). "Erastin was found to reduce cell viability, while CMTM5 knockdown improved cell viability in erastin‐induced glioma cells, whereas WWP2 downregulation impaired these changes." (PMID 39166861, 2024). "The present study provides more evidence of the inhibitory effect of WWP2 knockdown in glioma and the related mechanism." (PMID 39166861, 2024). "Further, WWP2 knockdown was found to enhance the stability of LATS2 protein in glioma cells, indicating the potential effect of WWP2 on the ubiquitination of LATS2 protein." (PMID 39166861, 2024). "CMTM5 exerted a suppressive effect on cell growth and invasion and promoted ferroptosis of glioma cells by regulating the WWP2/LATS2 pathway." (PMID 39166861, 2024). "Collectively, these findings suggest that CMTM5 knockdown augmented cell growth and suppressed ferroptosis of glioma cells by regulating WWP2." (PMID 39166861, 2024). "CMTM5 regulated Hippo/YAP signaling to inhibit cell growth and invasion and to promote ferroptosis in glioma by regulating WWP2‐mediated LATS2 ubiquitination, thereby attenuating glioma progression." (PMID 39166861, 2024). "WWP2 was found to be frequently upregulated in human cancers, such as glioma and oral and lung cancers." (PMID 36803368, 2023). "S251 of SOX2 is phosphorylated by DNA-PK under normal conditions, preventing the ubiquitination and degradation of SOX2 mediated by WWP2 and maintaining the stem status of glioma stem cells." (PMID 36091384, 2022). "More importantly, a previous study reported the suppressive effect of WWP2 silencing in glioma." (PMID 39166861, 2024). "Collectively, this is the first study to demonstrate that CMTM5 overexpression may suppress cell growth and invasion and promote ferroptosis of glioma cells by reducing WWP2 expression." (PMID 39166861, 2024). "Knockdown of WWP2 reversed the promotion of CMTM5 knockdown on glioma cell viability." (PMID 39166861, 2024). "Besides, LATS2 downregulation promoted cell viability, proliferation, migration, and invasion of glioma cells, whereas WWP2 knockdown or CMTM5 overexpression reversed these changes caused by LATS2 downregulation." (PMID 39166861, 2024). "Here, we identified LATS2 as a substrate protein of WWP2 in glioma." (PMID 39166861, 2024). "In conclusion, we propose that CMTM5 may regulate Hippo/YAP axis to suppress cell growth and invasion and accelerate cell ferroptosis in glioma by inhibiting WWP2‐mediated LATS2 ubiquitination." (PMID 39166861, 2024). "However, LATS2 knockdown‐mediated reduction of Fe2+, lipid ROS, and MDA levels in erastin‐induced glioma cells was reversed by WWP2 knockdown or CMTM5 overexpression." (PMID 39166861, 2024). "Therefore, we speculated that WWP2 might regulate Hippo/YAP signaling axis‐mediated glioma progression by mediating LATS2 ubiquitination." (PMID 39166861, 2024). "However, the relationship between CMTM5 and WWP2 in glioma remains to be further elucidated." (PMID 39166861, 2024). "Moreover, Co‐IP analysis validated the interaction between CMTM5 and WWP2 in glioma cells." (PMID 39166861, 2024). "However, it is still unclear whether the CMTM5/WWP2/LATS2 axis is involved in angiogenesis in glioma and the treatment of glioma with bevacizumab." (PMID 39166861, 2024).
glioma (continued). "Similarly, the WWP2 (WW domain-containing E3 ubiquitin protein ligase 2)-PTEN axis has been implicated in prostate, endometrial, hepatocellular, oral squamous cell cancers, and glioma, where WWP2 overexpression correlates with aggressive tumor phenotypes and poor prognosis." (PMID 40002221, 2025). "Knockdown of WWP2 abolished CMTM5 silencing‐promoted cell growth and invasion and CMTM5 silencing‐suppressed ferroptosis of glioma cells." (PMID 39166861, 2024). "Here, we found that WWP2 knockdown‐mediated reduction of WWP2 and YAP1 expression and elevation of LATS2 and p‐YAP1 levels in glioma cells was reversed by the combination of sh‐WWP2 and sh‐CMTM5 transfection." (PMID 39166861, 2024). "This is the first study to demonstrate that CMTM5, which suppressed WWP2 expression through interacting with WWP2 protein, inhibited cell growth and promoted ferroptosis by attenuating WWP2‐mediated LATS2 ubiquitination and degradation, thereby alleviating glioma progression." (PMID 39166861, 2024). "LATS2 knockdown promoted glioma cell viability, Erastin treatment suppressed cell viability and the variation tendencies of cell viability by sh‐LATS2/sh‐WWP2/oe‐CMTM5 transfection in erastin‐induced glioma cells mimicked those in glioma cells without erastin treatment." (PMID 39166861, 2024). "we did not investigate whether CMTM5/WWP2/LATS2 signaling affects DNA repair enzyme O6Meg DNA methyltransferase (MGMT) status in glioma." (PMID 39166861, 2024). "Thus, MG132, a proteasome inhibitor, was added to glioma cells with/without sh‐WWP2 transfection." (PMID 39166861, 2024).
heart failure (5 papers, 2020 to 2024). Inability of the heart to pump blood at an adequate rate to meet tissue metabolic requirements. "Previous studies hinted at the WW domain-containing E3 ubiquitin protein ligase 2 (WWP2) involving in heart failure and endothelial injury." (PMID 38591063, 2024). "WWP2 was associated with oxidative stress-mediated VSMC injury in different cardiovascular diseases, such as AS, ischemia-reperfusion injury, cardiomyopathy and heart failure, suggested that WWP2 could be a significant target for treating several cardiovascular diseases." (PMID 38166045, 2024). "Therefore, targeted knockout of WWP2 in vascular smooth muscle cells may be a new tool for the prevention and treatment of hypertensive vascular diseases such as stroke, kidney and heart failure." (PMID 32627301, 2020). "Therefore, investigating the role and molecular mechanism of WWP2 in VSMCs phenotypic transformation as well as proliferation and migration may provide new insights into the treatment of hypertensive vascular diseases such as stroke, kidney and heart failure." (PMID 32627301, 2020).
atherosclerosis (4 papers, 2020 to 2024). A disease characterized by the build-up of fatty material and calcium deposition in the arterial wall resulting in partial or complete occlusion of the arterial lumen. "WWP2 is involved in vascular endothelial injury 123-124, SMURF1 in atherosclerosis 135-137 and pulmonary hypertension 127-132, and SMURF2 in myxomatous mitral disease 158-160 and vascular endothelial injury 168-170." (PMID 33110392, 2020). "In conclusion, our results suggest that WWP2 protects against atherosclerosis progression via the PDCD4/HO-1 pathway, which may provide a novel treatment strategy for atherosclerosis." (PMID 35983977, 2022). "WWP2 is a HECT-type E3 ubiquitin ligase that regulates various physiological and pathological activities by binding to different substrates, but its role in atherosclerosis (AS) remains largely unknown." (PMID 35983977, 2022).
hepatocellular carcinoma (4 papers, 2019 to 2025). A malignant tumor that arises from hepatocytes. "Gankyrin also prevents POU5F1 degradation in hepatocellular carcinoma (HCC) by inhibiting the interaction of POU5F1 with WW domain containing E3 ubiquitin protein ligase (WWP2;." (PMID 31744479, 2019). "For instance, WWP2 knockdown was found to suppress malignant activities by regulating the AKT pathway and augment the antitumor effect of doxorubicin in hepatocellular carcinoma." (PMID 39166861, 2024). "Moreover, in hepatocellular carcinoma (HCC), WWP2, another WWP family member, is frequently overexpressed, with higher levels correlating with tumor recurrence and lower survival rates." (PMID 39949609, 2024).
lung carcinoma (4 papers, 2021 to 2025). "Elevated WWP2 has been linked to the development of LUAD, and the STAT6-WWP2-p27 axis is known to regulate cell proliferation, cell cycle progression, and apoptosis in lung cancer." (PMID 39661479, 2025). "The “new” autoantibodies in our panel target TAAs like DCTPP1, GIMAP4, WWP2, MGMT, KCMF1, and GDA, which have demonstrated links to lung cancer pathogenesis." (PMID 39661479, 2025).
endometrial cancer (3 papers, 2015 to 2023). Primary or metastatic malignant neoplasm involving the endometrium (mucous membrane that lines the endometrial cavity). "As an additional support of the competition model, siRNAs that target endogenous p85α or WWP2 decreased the interaction of PTEN with WWP2 or p85α, respectively, in an endometrial cancer cell line HEC1A that expresses high levels of p85α and WWP2." (PMID 26222500, 2015).
fibrosis (3 papers, 2019 to 2024). the formation of excess fibrous connective tissue in an organ or tissue in a reparative or reactive process. "We have previously shown that WWP2 is a regulator of pathological cardiac fibrosis through the control of a profibrotic gene network conserved in rat and human heart disease characterized by diffuse myocardial remodeling and fibrosis." (PMID 36450710, 2022). "Here, starting from the identification of a pro-fibrotic gene network conserved in rat and human heart disease characterized by diffuse myocardial remodeling and fibrosis, we identified WWP2 as a regulator of pathological cardiac fibrosis." (PMID 31399586, 2019). "We did not observe any difference at the mRNA level of SMAD2 in WWP2Mut/Mut cardiac (myo)fibroblasts or in cells overexpressing or silencing the WWP2-N/FL isoforms, suggesting that WWP2 function on cardiac fibrosis could be exerted through SMAD2 interaction and ubiquitination at the protein level." (PMID 31399586, 2019).
multiple myeloma (3 papers, 2016 to 2024). "Overexpression of WWP2 limits the progression of multiple myeloma and enhances the sensitivity of cells to bortezomib therapy." (PMID 39166861, 2024).
myocardial hypertrophy (3 papers, 2022 to 2025). "In the signaling pathway of cardiac hypertrophy, BAF55 suppresses ubiquitin-protein ligase WWP2-mediated PARP1 ubiquitination." (PMID 39865120, 2025).
prostate carcinoma (3 papers, 2014 to 2025). A carcinoma that arises from epithelial cells of the prostate gland. "Importantly, WWP2 has been proposed to be an oncoprotein in prostate cancer by targeting the phosphatase and tensin homologue deleted on chromosome TEN (PTEN) for proteasomal degradation." (PMID 25621296, 2014). "The results revealed that compared with normal tissues, WWP2 was significantly up-regulated in four tumor types: liver hepatocellular carcinoma (LIHC), cholangiocarcinoma (CHOL), prostate cancer (PRAD), and stomach adenocarcinoma (STAD)." (PMID 41387673, 2025). "WWP2 has been identified to ubiquitinate and regulate PTEN in prostate cancer cells." (PMID 35780838, 2022). "Furthermore, it was recently reported that WWP2-mediated depletion of PTEN, which is a negative regulator of the PI3K/AKT signaling pathway, consequently elevated AKT signaling activity, and rendered prostate cancer cell lines resistant to stress-inducible cell mortality." (PMID 25621296, 2014).
viral infection (3 papers, 2010 to 2024). "Following the overexpression or knockdown of WWP2 in 293T cells and interferon system‐deficient U3A cells, we infected the cells with JEV and measured viral infection using qPCR and plaque assays." (PMID 39159062, 2024). "Conversely, viral infection exhibited an increase following the knockdown of intracellular WWP2 expression." (PMID 39159062, 2024). "The results revealed a significant decrease in viral infection after WWP2 overexpression compared with controls and an increase in viral replication after the knockdown of intracellular WWP2 expression." (PMID 39159062, 2024). "The results demonstrated a significant reduction in viral replication in cells after the overexpression of WWP2 and an increase in viral infection after knocking down WWP2." (PMID 39159062, 2024). "Due to that WWP2 is involved in a wide range of biological functions, dysregulation of WWP2 leads to various disease states, such as neurodegeneration, cancer, inflammation and viral infections." (PMID 37359559, 2023). "In contrast, WWP2, another Nedd4-family ubiquitin ligase, which has been also identified as a UL56-interacting protein by a yeast two-hybrid screen, showed no remarkable change after viral infection." (PMID 20682038, 2010).
acute myeloid leukemia (2 papers, 2024 to 2025). Acute myeloid leukemia (AML) is a group of neoplasms arising from precursor cells committed to the myeloid cell-line differentiation. "Interestingly, both TMEM127 and WWP2 were recently shown to deplete surface MHCI in acute myeloid leukemia (AML) cells." (PMID 41135677, 2025). "In acute myeloid leukemia (AML), the sushi domain containing 6 (SUSD6) interacts with transmembrane protein 127 (TMEM127) and MHC-I, recruiting the E3 ubiquitin ligase WWP2." (PMID 39223632, 2024).
cardiomyopathy (2 papers, 2024 to 2025). A disease of the heart muscle or myocardium proper. "The E3 ligase WWP2 has been identified as a key regulator of cardiac fibrosis and dysfunction in cardiomyopathy." (PMID 41362701, 2025).
colorectal cancer (2 papers, 2019 to 2022). A primary or metastatic malignant neoplasm that affects the colon or rectum. "To examine the potential of WWP2 to ubiquitinate NDP52, OPTN, and SQSTM1 in cells, we cotransfected Myc-tagged WWP2 and the corresponding FLAG-tagged autophagy receptors in the HCT116 colorectal cancer cell line." (PMID 35331737, 2022). "Linc02023 suppresses colorectal cancer growth through blocking the interaction between PTEN and WWP2 and enhancing PTEN stability." (PMID 31592114, 2019).
embryonal carcinoma (2 papers, 2016 to 2025). A non-seminomatous malignant germ cell tumor characterized by the presence of large germ cells with abundant cytoplasm resembling epithelial cells, geographic necrosis, high mitotic activity, and pseudoglandular and pseudopapillary structures formation. "OCT-4 is ubiquitinated by Wwp2 and degradated during differentiation of embryonal carcinoma cell line but does not affect OCT-4 protein level in embryonic stem cells." (PMID 27275321, 2016).
ischemic cardiomyopathy (2 papers, 2022 to 2025). Ischemic cardiomyopathy is a cardiomyopathy in which a weakness in the muscle of the heart due to inadequate oxygen delivery to the myocardium with coronary artery disease being the most common cause. "We identify a pro-fibrogenic macrophage subtype in non-ischemic cardiomyopathy, and demonstrate that WWP2 is a key regulator of IRF7-mediated Ccl5/Ly6chigh monocyte axis in heart fibrosis." (PMID 36450710, 2022).
liver fibrosis (2 papers, 2021 to 2023). "PPM1G plays a fundamental role in increasing liver fibrosis by negatively regulating the effect of WWP2 on Notch3 degradation." (PMID 33952716, 2021).
lung adenocarcinoma (2 papers, 2022 to 2025). A carcinoma that arises from the lung and is characterized by the presence of malignant glandular epithelial cells. "Downregulation of WWP2 decreased obviously lung adenocarcinoma proliferation." (PMID 36211818, 2022).
melanoma (2 papers, 2014 to 2020). A malignant, usually aggressive tumor composed of atypical, neoplastic melanocytes. "UV exposure can trigger PTEN interaction with wild-type melanocortin-1 receptor variants, which protects PTEN from WWP2-mediated degradation, leading to AKT inactivation in melanoma." (PMID 24571667, 2014). "Further studies are necessary to elucidate whether MTII regulates the expression or activities of src/casein kinase 2 or ubiquitin ligases (such as WWP1 and WWP2), thereby modulating PTEN expression in melanoma cells." (PMID 31968661, 2020).
pancreatic cancer (2 papers, 2025). "For instance, transcription factor EB (TFEB) K91la inhibits the interaction with WW domain containing E3 ubiquitin protein ligase 2 (WWP2) in pancreatic cancer cells." (PMID 40994548, 2025). "For instance, TFEB K91la disrupts its interaction with E3 ubiquitin ligase WWP2, lowering TFEB ubiquitination and proteasomal degradation in pancreatic cancer." (PMID 40994548, 2025). "Lactylation at the Lys91 site of TFEB inhibits its interaction with WWP2, stabilising TFEB by obstructing WWP2-mediated proteasomal degradation pathways and thereby promoting autophagy in pancreatic cancer." (PMID 41463025, 2025).
Sepsis (2 papers, 2024). Sepsis is defined as life-threatening organ dysfunction caused by a dysregulated host response to infection. "However, the precise implications of WWP2 in sepsis-induced cardiac injury, along with the underlying mechanisms, remain enigmatic." (PMID 38591063, 2024). "To meticulously examine the influence of WWP2 on sepsis-induced cardiac injury, we initiated our investigation by performing tail vein injections of AAV-CTNT-WWP2sh." (PMID 38591063, 2024). "To gain further insight into the distinct role of cardiac-specific WWP2, we executed tail vein injections of AAV-CTNT-Flag-WWP2, succeeded by intraperitoneal LPS injections 14 days later to establish the sepsis model." (PMID 38591063, 2024). "Continuing our pursuit of understanding the molecular underpinnings behind WWP2’s regulation of sepsis-induced myocardial injury and cardiomyocytes ferroptosis, our focus turned to the pivotal enzyme acyl-CoA synthetase long-chain family member 4 (FACL4)." (PMID 38591063, 2024). "WWP2 assumes a critical role in safeguarding the heart against injury induced by sepsis via regulating FACL4 to inhibit LPS-induced cardiomyocytes ferroptosis." (PMID 38591063, 2024). "In conclusion, this study conducted in vitro and in vivo experiments to investigate how WWP2 regulates oxidative stress imbalance and ferroptosis in the context of sepsis-induced cardiac injury." (PMID 38591063, 2024). "Across both in vivo and in vitro sepsis models, a consistent trend of decreased WWP2 protein expression was observed." (PMID 38591063, 2024). "Intriguingly, WWP2 exhibited a notable capacity to suppress these detrimental processes triggered by sepsis-induced conditions." (PMID 38591063, 2024). "In summary, our observations collectively pointed to the downregulation of WWP2 within cardiomyocytes affected by sepsis." (PMID 38591063, 2024). "Cardiac-specific overexpression of WWP2 protected heart from sepsis induced mitochondrial oxidative stress, programmed cell death and cardiac injury, while knockdown or knockout of WWP2 exacerbated this process." (PMID 38591063, 2024). "The protein level of WWP2 was downregulated in cardiomyocytes during sepsis." (PMID 38591063, 2024). "Notably, we observed a notable reduction in ferroptosis and cardiac injury within WWP2 knockout mice after FACL4 knockdown during sepsis." (PMID 38591063, 2024). "Therefore, we dug deeper into WWP2’s influence on cardiomyocytes ferroptosis within the sepsis cardiac injury model." (PMID 38591063, 2024). "Second, while we utilized myocardium-specific WWP2 intervention vectors to investigate the impact of WWP2 on LPS-induced myocardial injury and ferroptosis, we have not explored the functional and mechanistic aspects of systemic sepsis-related damage in other organs in WWP2KO mice." (PMID 38591063, 2024).
serous carcinoma (2 papers, 2014 to 2022). "We reported that WWP2 is genetically deleted and down-regulated in a significant number of ovarian high-grade serous carcinomas and overexpression of WWP2 suppresses tumor development and causes cell cycle arrest." (PMID 25356737, 2014).